MIR4315-1 (microRNA 4315-1)
Synonyms: hsa-mir-4315-1
Gene: MicroRNA gene on chromosome 17 (45,475,363 to 45,475,435, reverse strand). Ensembl gene ENSG00000284055.
Homologues: Paralogues in human: MIR4315-2 (100% identical).